IL10 (interleukin 10)
Diseases named in the same sentence as IL10 in open-access papers (continued):
Sharing a sentence is not in itself a finding about the gene and the disease.
melanoma (continued). "A recent study testing the effect of immunomodulatory expression quantitative trait loci (eQTLs) identified an association between eQTL in IL-10/BATF3 locus on 1q32 and survival in melanoma, complementing other established clinico-pathological prognostic markers." (PMID 31113486, 2019). "In addition, β-catenin-overexpressed melanomas inhibit the production of IFN-γ by melanoma-specific cytotoxic lymphocytes (CTLs) in an interleukin (IL)-10-independent manner and were more resistant to CTL lysis in vitro and in vivo." (PMID 31775797, 2019). "This can be partially associated with increased IL-10 secretion, thus the miR-30b/30d-GALNT7-IL-10 axis could be an explanation of the immunosuppressive behavior of melanoma." (PMID 30866509, 2019). "While normally anchored to keratinocytes by E-cadherin, LCs acquire motility under the influence of TGF-β and thus promote melanoma progression via immune suppression, including peripheral tolerance, the expansion of Tregs and the stimulation of IL-10 production in the TME." (PMID 31750245, 2019). "Moreover, these EVs were able to favor melanoma re-growth in vivo, which was accompanied by an increase in Arginase 1 and IL10 gene expression levels by stromal cells and an increase in genes related to DNA repair, cell survival and stemness in tumor cells." (PMID 31597943, 2019). "Interestingly, it has been recently demonstrated in advanced melanoma that IL-10 levels in nivolumab responders were significantly higher than those in the non-responders supporting our current findings." (PMID 30108590, 2018). "They found that IL-27 might induce suppressive molecules such as PD-L1 and IL-10 and thus immunosuppressive responses and melanoma progression." (PMID 30581461, 2018). "On the other hand, it has been reported that elevations in the pre-therapy serum concentrations of the cytokines IFN-γ (P < 0.0001), IL-6 (P < 0.0007), and IL-10 (P < 0.0001) are predictive of treatment efficacy in patients with advanced melanoma receiving nivolumab." (PMID 29623257, 2018). "Additionally, in a melanoma mouse model it was observed that HMGB1 release promoted M2 macrophage recruitment and IL10 expression and was associated with tumor growth and metastasis." (PMID 29472602, 2018). "Thus, our findings suggest that the axis IL-10/claudin-10 is a promising target for the development of therapeutic agents against aggressive melanoma." (PMID 29145406, 2017). "Finally, recent data obtained on melanoma and breast cancer indicated that there is an association between the expression of ICOS and the production of immunosuppresive interleukin IL-10 in Tregs that results in suppression of T cells and dendritic cells." (PMID 29285252, 2017). "In order to replicate a tumor endothelial environment we utilized several cocktails of conditioned media from tumor cell lines (LLC (lung cancer), B16 (melanoma), RM-1 (prostate cancer), GL-261 (glioma), 4T1 (breast cancer)), as well as tumor associated cytokines (PGE-2, TGF-beta, and IL-10)." (PMID 28404894, 2017). "Thus, our results demonstrate that the axis IL-10/claudin-10 is a suitable target to control the behavior of melanoma cells." (PMID 29145406, 2017). "The concentration of serum IL-10 in melanoma is 8.75×10−12 g/cm3." (PMID 28724377, 2017). "Consequently, such data supported the notion that the influence of B-1 lymphocytes in the behavior of melanoma cells depends upon the endogenous IL-10 levels." (PMID 29145406, 2017). "In further support for a potential role of TAMs and IL-10 in melanoma is the presence of IL-10-producing TAMs in human melanoma metastases as revealed by the presence of CD163+ IL-10+ cells infiltrating human metastases in areas with high cytoplasmic HMGB1 expression." (PMID 27426915, 2016). "Moreover, it was reported that IL-10 repressed tumor growth and the metastatic potential of melanoma cells by inhibiting the expression of angiogenic factors and, thereby, vascularization." (PMID 26631117, 2015).
melanoma (continued). "Here we showed that miR-15a, miR-185, and miR-211 mimics inhibited and miRNA inhibitors increased the proliferation of IL-10-treated melanoma cells through IL-10 signaling, since the silencing of IL-10Rα cancelled the effects of miRNA inhibitors on the proliferation." (PMID 26631117, 2015). "Irrespectively of the effects of IL-10 on the immune response, the direct effects of this cytokine on melanoma cell themselves have been only incompletely addressed, although one study suggested that IL-10 might function as an autocrine growth factor." (PMID 26631117, 2015). "Thus, in the setting of lymphatic dysfunction, expression of inflammatory cytokines as well as IL-10 was decreased in draining LNs following subcutaneous injection of B16 melanoma cells." (PMID 26098776, 2015). "Our results support a key role of IL-10Rα in the development and progression of melanoma and suggest that the IL-10/IL-10 receptor system may become a new therapeutic target for melanoma treatment." (PMID 26631117, 2015). "Therefore, our data add to our knowledge about the significance of IL-10Rα post-transcriptional regulation in the characteristics of malignancy of melanoma, independently from the questioned immunostimulant or immunosuppressive role of IL-10." (PMID 26631117, 2015). "Given that very few data are available about the post-transcriptional regulation of the IL-10 system and its role in melanoma cell behavior, we aimed at investigating the involvement of miRNAs in the expression levels of IL-10 and its receptors in cutaneous and uveal melanoma cells." (PMID 26631117, 2015). "In contrast, other studies indicate that IL-10 may augment the effects of anti-melanoma vaccination or inhibit melanoma metastasis through activation of NK cells." (PMID 26631117, 2015). "Moreover, IL-10 can exert antitumoral activity in gliomas, melanomas, and breast and ovarian carcinomas, through a mechanism involving MHC-I downregulation, thus inducing NK-mediated tumor cell lysis." (PMID 24901008, 2014). "Indeed, IL-10 blockade by an anti-IL-10 mAb, administered in monotherapy at the site of tumor challenge, led to a significant delay in melanoma growth, reminiscent of what observed in different experimental settings." (PMID 23663506, 2013). "We found that β-catenin directly promote transcription of immunosuppressive cytokine IL-10 in human melanoma, and protein expression of β-catenin was correlated with expression of IL-10 when evaluated by immunohistochemical analysis of melanoma tissues samples." (PMID 23755373, 2013). "Beside monocytes, fully differentiated DC can be recruited to the tumor microenvironment, where they may lose their characteristic CD1a expression through the suppressive action of IL-10, as shown for melanoma metastases." (PMID 24324467, 2013). "Indeed, the observation that TIL purified from melanoma lesions exerted a regulatory activity in an IL-10 dependent fashion confirmed this idea." (PMID 23663506, 2013). "Consistent with this hypothesis, we found that IL-27 could induce suppressive molecules such as PD-L1, and to a lesser extent IL-10, in melanoma cells, and that the in situ expression of IL-27 in melanoma correlated with those of PD-L1 and IL-10." (PMID 24130734, 2013). "On the other hand, other studies have suggested that IL-10 may promote angiogenesis in a melanoma cell model, by inhibiting macrophage functions and inducing tumor and vascular cell proliferation." (PMID 23967403, 2013). "The melanoma derived factors also inhibited the effector function of melanoma-specific CTLs in a β-catenin-dependent, but interestingly IL-10-independent manner, indicating that other immunosuppressive molecules are also involved in the β-catenin-induced immunosuppression." (PMID 23755373, 2013). "Elevated plasma levels of IL-10 were also reported for patients with melanomas." (PMID 23950929, 2013).
melanoma (continued). "Moreover, melanoma sections stained with an anti-IL-10 mAb demonstrated the presence of the cytokine in the tumor microenvironment (data not shown)." (PMID 23663506, 2013). "In addition, two recent reports described the existence of suppressor IL-10-producing neutrophils during a bacterial infection and melanoma." (PMID 22577359, 2012). "This suggests a more complex regulation of IL-10 expression in this melanoma model." (PMID 22674057, 2012). "The presence of the AA genotype (lower IL-10 production) has also been associated to the development of prostate cancer and renal cell carcinoma but not conclusively to melanoma susceptibility." (PMID 18221542, 2008). "IL-10 has also been shown to down-regulate ICAM-1 in human melanoma cells." (PMID 15518595, 2004). "In addition, strong expression of IL-10 mRNA and of biologically active IL-10 was detected in 3 out of 13 melanoma cell lines." (PMID 7981073, 1994). "The production of biologically active IL-10 by melanoma cell lines suggests that IL-10 mRNA in melanoma lesions may derive at least in part from the tumour cells themselves." (PMID 7981073, 1994). "The presence of IL-10 in melanoma lesions may contribute to the postulated 'paralysis' of an anti-melanoma immune response." (PMID 7981073, 1994). "Moreover, CM from B16 melanoma cells induces M2-like polarisation in BMDMs through IL-10 and TGFβ." (PMID 40547518, 2025). "This may imply that cutAEs in melanoma, which induce an IL-10 response, should be treated fast and effectively to reduce cutAEs early and prevent further production of IL-10, as prolonged treatment with corticosteroids has been shown to blunt antitumor efficacy." (PMID 38539560, 2024). "In addition, PEGylated IL-10 has been found to induce systemic immune activation in melanoma patients, and its use in combination with Nivolumab induced a manageable toxicity and preliminary anti-tumor activity in melanoma patients (10% patients with objective responses)." (PMID 36768978, 2023). "Interestingly, co-culture of B cells with different cancer cell lines yielded different expression levels of IL-10, with sarcoma cells failing to stimulate IL-10 production in B cells, in contrast to Friend murine leukemia virus gag-expressing and melanoma cells which induced B cell IL-10 secretion." (PMID 37612756, 2023). "Lastly, A375 displayed the most advanced stage of melanoma development by clear melanoma expansion into the reconstructed dermis and by the secretion of a plethora of (anti-)inflammatory cytokines (GM-CSF, IL-6, IL-8, IL-10, M-CSF, and TGFβ) involved in immune suppression and melanoma progression." (PMID 37345186, 2023). "Furthermore, in combination with the hypoglycemic agent metformin, a drug largely used for type 2 diabetes, the EGCG inhibited the NF-kB/STAT3 signaling pathways, resulting in reduced melanoma growth and metastatic potential, and decreased pro-inflammatory mediators such as IL-6, IL-10 and TNF-α." (PMID 36768978, 2023). "Moreover, IL-10 in itself, which is produced by melanoma cells as an autocrine factor, appeared to be a more potent inhibitor of ILC2 secretory activity than TGF-β and is known for its capability to further stimulate the suppressive activity of both Treg and MDSCs." (PMID 36765891, 2023). "A375 showed cell-cycle arrest, indicating that IL-10 could slow down the cell cycle of melanoma." (PMID 35893303, 2022). "Interestingly, our data indicate that melanoma progression appears to be associated with changes in the number of LTA+ rather than IL-10+ B cell numbers, suggesting a more relevant functional role for LTA+ B cells." (PMID 34359321, 2021). "Here we evaluated whether IgG4, previously reported to be overexpressed in melanoma and other cancers with poor outcomes, can stimulate M2a and M2b macrophages to adapt immunosuppressive states and to enhance production of IL-10 and other immunomodulatory mediators." (PMID 33628623, 2021).
melanoma (continued). "Moreover, intratumoral IL-10 expression has been demonstrated to correspond with invasion depth and the metastatic potential of primary melanoma cells, while an increased serum level of IL-10 seems to render poor prognosis in advanced melanoma patients." (PMID 34944793, 2021). "After establishing the boosting effect of MAFs on the IL-10 production of macrophages in vitro, we wondered if the degree of immunosuppression exhibited by MAFs may correlate with well-defined clinical parameters of melanoma patients." (PMID 34944793, 2021). "It has been accepted that in solid tumors including breast, ovarian, melanoma and gastric cancers, pDCs were shown to be largely dysfunctional with decreased capacity to produce IFNα and with induction of Tregs that produce IL-10 and TGFβ, which further support tumor progression." (PMID 34442012, 2021). "Moreover, IL-6, which is also secreted by CAFs, induces IL-10 production by melanoma cells." (PMID 33171792, 2020). "Due to the striking higher release of the M2 polarizing cytokine IL-10 by the melanoma model, it was next determined whether Mel-RhS-derived culture supernatants could interfere with the differentiation of monocytes into monocyte-derived dendritic cells (moDCs)." (PMID 32507967, 2020). "Therefore, we believe that MSCs that were injected in B16F10-treated mice during the progressive stage of melanoma growth adopted immunosuppressive MSC2 phenotype and in a TGF-β and IL-10-dependent manner attenuated antitumor immune response, resulting in increased melanoma growth." (PMID 32695181, 2020). "Moreover, BRAFV600+ melanoma cell lines secrete immunosuppressive cytokines such as interleukin 10 (IL-10), vascular endothelial growth factor (VEGF), and interleukin 6 (IL-6), which promote the recruitment of regulatory T cells and myeloid-derived suppressor cells." (PMID 32731406, 2020). "Therefore, taken together, reduced levels of RANTES, IL-3 and IL-10 may be involved in the anti-melanoma immune response under NAM treatment." (PMID 33028392, 2020). "Furthermore, IL-10 has a known immunosuppressive effect in melanoma." (PMID 33028392, 2020). "Besides the evaluation of CXCL1 levels in the melanoma microenvironment, we also analyzed the effect of the fatty acids treatment on in vitro and in vivo levels of IL-6, a pro-inflammatory cytokine, and IL-10, a classical anti-inflammatory cytokine." (PMID 31374840, 2019). "Furthermore, Kalli and co-workers showed that application of anti-IL-10 monotherapy partially inhibited the B16 melanoma and anaplastic large cell lymphoma development, while vaccination with tumor antigen stimulated DCs and anti-IL-10 Abs provided complete protection against melanoma." (PMID 29954431, 2018). "Moreover, IL10 suppresses melanoma tumor growth and metastasis." (PMID 26956044, 2016). "Moreover, GP-B1 not only significantly inhibited the growth of cancer cells, but also improved cellular immune response by increasing levels of tumor necrosis factor-α (TNF-α), interferon-γ (IFN-γ), interleukin-10 (IL-10) and interleukin-12 (IL-12) observed in the serum of melanoma-B16-bearing mice." (PMID 27708693, 2016). "Along this line, recent evidences suggested that inhibition of the MAPK pathway in melanoma cells may result in the block of the production of tumor-derived immunosuppressive or proangiogenetic factors including IL-6, IL-10 and VEGF that are essential for cancer immune evasion and growth." (PMID 27563819, 2016). "Moreover, GP-B1, the acidic polysaccharide obtained from GpM, not only significantly inhibited the growth of cancer cells, but also improved cellular immune response with increased levels of TNF-α, IFN-γ, IL-10 and IL-12 in the serum of melanoma-B16-bearing mice." (PMID 27708693, 2016). "Moreover, what are the direct effects of IL-10 on melanoma cells and whether the latter differ from normal melanocytes in their responsiveness to the cytokine is presently unclear." (PMID 26631117, 2015).
melanoma (continued). "Thus, it could be argued the IL-10/IL-10 receptor system may become a new epigenetic therapeutic target for melanoma treatment." (PMID 26631117, 2015). "One of the mechanisms involved in immune escape by melanoma cells involves down regulation of the proinflammatory microenvironment by regulatory T cells (Treg) via the release of immunosuppressive cytokines such as IL-10 and TGF-β, among several other immune suppressive mechanisms." (PMID 24457057, 2014). "Wnt/β-catenin signaling might be involved in immunosuppression in melanoma, as high levels of nuclear β-catenin in melanoma cells impaired maturation of DCs at least in part through increased production of IL-10 and inhibited IFN-α production by melanoma-specific CTLs." (PMID 24743024, 2014). "In order to understand whether the effects mediated by IL-10 neutralization were melanoma-specific or could be replicated in a different unrelated type of tumor, the same experiment was performed using mouse anaplastic large cell lymphoma (ALCL) cells (ALK+ VAC cells,) as challenging tumor." (PMID 23663506, 2013). "In addition, in in vitro experiments using human melanoma cell lines, we showed that IL-27 can induce the expression of IL-10 and, more consistently, that of PD-L1 in these cells, suggesting that an autocrine loop may operate in these cases." (PMID 24130734, 2013). "Similar to the RAS/BRAF/MAPK signaling activation, down-regulation of STAT3 by lentiviral shRNA in STAT3-activated melanoma resulted in inhibition of multiple immunosuppressive cytokines, including IL-6, IL-10, and VEGF, indicating that STAT3 inhibitors may also be useful for immunotherapy." (PMID 23755373, 2013). "We could detect IL-10 release especially in some melanoma patients as well as healthy donors." (PMID 22539948, 2012). "The analysis of IL-10 promoter -1082 polymorphism in the sixteen patients showed a positive correlation between AA genotype, accompanied by lower in vitro IL-10 production by stimulated PBMC, and faster melanoma progression after lymph nodes surgery (p = 0.04)." (PMID 18221542, 2008). "Tumour-infiltrating cells, however, could also be a source of IL-10 in melanoma tissues." (PMID 7981073, 1994). "In melanoma, hypoxia leads to cell necrosis and release of HMGB1, which interacts with RAGE to activate M2-type macrophages to secrete interleukin-10 (IL - 10), thereby promoting melanoma growth and metastasis." (PMID 40969278, 2025). "In the melanoma cohort, baseline cytokine correlations also pointed to shared regulatory mechanisms, particularly between TNF-α and IL-10." (PMID 41020868, 2025). "Melanoma and the melanoma tumor microenvironment secret immunosuppressive molecules and factors such as IDO, PGE2, TGF-β, prostaglandins, and IL-10, which can downmodulate NK cell-activating receptors and can inhibit NK cell activity." (PMID 40805135, 2025). "B cell-derived IL10 has also been shown to contribute to M2 polarization in a melanoma model, and in colon cancer, B cell–derived γ-aminobutyric acid (GABA) enhances IL10+ macrophage populations, which in turn inhibit CD8+ T cell function." (PMID 41019045, 2025). "Microglia that are recruited to the site of melanoma through CSF1R and TREM2 and are exposed to C3 adopt a supportive phenotype characterized by IL-10 and TGF-β release, extracellular matrix remodeling, synaptic pruning, and reduction in cytotoxic signals." (PMID 41463339, 2025). "Despite a limited number of patients, this study provides preliminary insight into the potential predictive role of serum cytokines, TNF-α, IL-2 and IL-10 in patients diagnosed with NSCLC and melanoma undergoing anti-PD-1 immunotherapy with Nivolumab." (PMID 41020868, 2025). "S3QEL 1.2 impairs IL-10 production in vivo after LPS challenge and promotes the survival of mice bearing B16F10 melanoma by lowering tumor growth." (PMID 39841829, 2025).